RNU6-775P (RNA, U6 small nuclear 775, pseudogene)
Gene: Small nuclear RNA gene on chromosome 2 (55,451,004 to 55,451,099, reverse strand). Ensembl gene ENSG00000238619.
Homologues: Orthologues: macaque U6 (94% identical), rat LOC120099400 (76% identical), mouse Gm23378 (75% identical), pig U6 (72% identical), rabbit U6 (69% identical). Paralogues in human: RNU6-221P (90% identical), RNU6-20P (78% identical), RNU6-1075P (77% identical), RNU6-1078P (77% identical), RNU6-1122P (77% identical), RNU6-1263P (77% identical), RNU6-38P (77% identical), RNU6-1130P (76% identical), RNU6-1145P (76% identical), RNU6-1316P (76% identical), RNU6-15P (76% identical), RNU6-16P (76% identical), and 1281 more.